SOX2 (SRY-box transcription factor 2)
Diseases named in the same sentence as SOX2 in open-access papers (continued):
Sharing a sentence is not in itself a finding about the gene and the disease.
breast cancer (continued). "Indeed, nuclear accumulation of FOXO1, but not that of other TFs, promotes SOX2 gene expression in breast cancer." (PMID 31844113, 2019). "Moreover, we discovered that KRT19 regulates CSC reprogramming and drug sensitivity in breast cancer and cancer stem cell-like cells, through mediating stemness (NANOG, OCT4, KLF4, and SOX2) and drug-resistant (ALDH1, ABCG2, ABCC1, and ABCB1) marker expression." (PMID 29747452, 2018). "Specifically, the shh-GLI1 pathway is promoted by Hh to induce OCT4 and SOX2 expression in breast cancer cells, which is crucial in TWIST-induced maintenance of mammosphere enrichment and self-renewal capacity, this finding is similar to the tumorigenicity of breast cancer cells in vivo." (PMID 29299179, 2017). "Furthermore complex interactions of Sox2 with its partner proteins and its relatively low expression rate compared with other ESC transcription factors in breast cancer could lead to variable outcomes." (PMID 28422735, 2017). "HOTAIR expression has been found to be necessary for the maintenance of the CSC phenotype in colon and breast cancer cell lines, and has recently been shown to regulate the breast cancer CSC population by transcriptionally inhibiting miR-34a, resulting in the upregulation of SOX2." (PMID 28430163, 2017). "Thus, it has been suggested that OCT4, SOX2 and NANOG may act as prognostic markers for breast cancer patients." (PMID 26580604, 2015). "Moreover, whereas no detectable levels of SOX2 protein were present in breast cancer cells, we detected a considerable level of SOX2 in ALDH-isolated colon cancer cells that was significantly reduced after Bozepinib treatment." (PMID 24946763, 2014). "In summary, our findings demonstrate that DNMT1/FOXO3a/FOXM1/SOX2 signaling promotes BCSC properties, which might contribute to tumor initiation and progression in breast cancer, and that targeting this signaling is a potential therapeutic strategy for breast cancer." (PMID 31296961, 2020). "Sox2 overexpression may result from SOX2 gene amplifications, however such amplifications are mainly reported in human serous ovarian cancers, lung squamous cell carcinomas, and glioblastomas, not in breast cancers." (PMID 33553286, 2020). "Moreover, RCOR2 replaces the need for Sox2 expression in somatic cell reprogramming, whereas Sox2 has a positive expression in the basal-like subtype, although it has not been directly related to the breast cancer subtype." (PMID 31296201, 2019). "Moreover, to be consistent with the previous studies reported in luminal breast cancer and ovarian cancer, we also observed that RASAL2 could modulate BCa cells stemness and EMT via MAPK pathway, in which the transcription factor SOX2 acted as an important bridge." (PMID 28182001, 2017). "Moreover, we recently published a link between E2/ERa signaling in breast cancer and pluripotency-like reporgramming, pointing to a mechanism where SOX2 can promote non-genomic E2 signaling that leads to nuclear phospho-Ser118-ERa, which exacerbates genomic ER signaling in response to E2." (PMID 25414831, 2014). "First, we found that, in the RAB4A-high MDA-MB-231 breast cancer cells, NUMB expression is essentially absent and NOTCH1 and SOX2 expression are easily visualized by western blot." (PMID 39463384, 2024). "Another study demonstrated that G9a ectopic overexpression did not affect the expression of SOX2 in GBM cell lines and an ER(−) breast cancer cell line." (PMID 36971192, 2023). "Of note, Jurkat cell-derived CM, which was generated from the overexpression of c-Myc/Oct4 as well as Sox2/Klf4 did not induce detectable changes in MTT-based viability and transwell invasion in 4T1.2 mammary tumor cells." (PMID 35547745, 2022). "Although stemness and EMT markers, such as SOX2, c-MYC, and NANOG, were downregulated in several YTHDC2-knocked-down breast cancer cells, a common target gene of YTHDC2 in breast cancer cells was not identified." (PMID 36245989, 2022).
breast cancer (continued). "Although the mRNA expression of stemness markers, such as SOX2, c-MYC, and NANOG, was reduced by YTHDC2 knockdown, the alteration of gene expression pattern was not the same for all of breast cancer cell lines." (PMID 36245989, 2022). "Of note, in luminal breast cancer, VEGF exposure was found to neither affect STAT3, SOX2, and MYC levels, nor CSCs." (PMID 31394796, 2019). "In patients without neurological symptoms, SOX2 antibodies were found in 77/259 (29.7%) patients with SCLC, but in only 15/238 (6%) of non-SCLC, 0/75 (0%) of breast cancer, 4/104 (4%) of ovarian cancer, and 8/414 (1.9%) of age matched healthy controls." (PMID 30445363, 2019). "Sox2, but not Oct4 or Nanog, overexpression was found in breast cancers and nuclear reprogramming of ER-positive Michigan Cancer Foundation-7 (MCF-7) cells yielded Sox2-overexpressing cells with enhanced BCSC characteristics." (PMID 30388742, 2018). "SOX2 and SOX2OT are differentially expressed in estrogen receptor positive and negative breast cancer tissues." (PMID 29732012, 2018). "Intriguingly, unlike the ER+ breast cancer cell lines which have robust Sox2 expression, we discovered that TNBC cells showed little to no expression of Sox2, and Sox2 was not a driver of the SRR2 reporter response." (PMID 28427212, 2017). "Although studies have been performed on SOX2 targeted silencing, the potential of OCT4 as a target for brain and breast cancer is not well documented." (PMID 26580604, 2015). "In case of breast cancer cell line (MCF7), there was no significant change in OCT4 and NANOG expression upon silencing EpCAM, while SOX2 was downregulated." (PMID 26176230, 2015). "SOX2 was also not induced in other oncogene-dependentmodels, such as ALK-translocated lung cancer cells treated withcrizotinib, HER2-amplified breast cancer cells exposed to lapatinibor BRAF-mutant melanoma cells treated with AZD6244." (PMID 25686219, 2015). "Moreover, patients with breast cancer having low mRNA levels of RET, MMP16, FN1, and SOX2 had better OS; however, the difference was not significant." (PMID 36601474, 2022). "In addition, patients with breast cancer with low mRNA levels of RET, MMP16, FN1, and SOX2 had better RFS, but this was not significant in the opposite groups (p > 0.05)." (PMID 36601474, 2022). "Besides, Sox2 and Klf4-overexpressing MSCs-derived CM also did not induce detectable changes in MTT-based viability and scratch-based migration in 4T1.2 mammary tumor cells." (PMID 35547745, 2022). "However, G9a did not affect Sox2 protein levels in MDA-MB-231 cells, an ER(-) breast cancer cell line, or in glioblastoma cell lines." (PMID 26492085, 2015). "Here, we show that the expression of SOX2 and SOX2OT is concordant in breast cancer, differentially expressed in estrogen receptor positive and negative breast cancer samples and that both are up-regulated in suspension culture conditions that favor growth of stem cell phenotypes." (PMID 25006803, 2014). "Additionally, we found that breast cancer cells that overexpress MEG8 have decreased the expression levels of some stem cell markers such as BMI1, SOX9 and KLF4 and in some cases also NANOG or SOX2, but not OCT4." (PMID 39706842, 2024). "Indeed, OPG upregulation promoted the pro-metastatic processes EMT and stemness in the non-carcinogenic (MCF-10A) and luminal breast cancer (T-47D, MCF-7) cells, through upregulating the mesenchymal (N-cadherin, SNAIL and ZEB1) and stemness (CD44, ALDH1, Nanog, Klf-4 and Sox2) markers." (PMID 39181873, 2024).
glioma (496 papers, 2007 to 2026). A benign or malignant brain and spinal cord tumor that arises from glial cells (astrocytes, oligodendrocytes, ependymal cells). "STAT3 has been reported to regulate a range of stemness-associated transcription factors, including Nanog, Sox2, and Oct4, in glioblastoma, thereby facilitating the formation and maintenance of glioma stem-like cells (GSCs)." (PMID 40759869, 2025). "In the context of glioma, the expression of SOX2 is associated with the preservation of stemness of GSCs." (PMID 38398118, 2024). "In the present study, we especially focused on SOX2 expression, because increased SOX2 levels are associated with a poor outcome for glioma patients." (PMID 36646875, 2023). "SOX2 is a marker of undifferentiated, proliferating cells and its expression is detected in all types of gliomas, in glioma cell lines and tumor-associated glial host cells." (PMID 37047365, 2023). "A recent study showed glioma ciliation is linked to glioma cell stemness and thru the master transcriptional regulator SOX2 and superenhancer KLHDC8A expression." (PMID 38630257, 2023). "In AKH-14 cultures, Sox2 expression was clearly associated with the filopodia-rich astrocyte phenotype, and the actin-rich glioma cells were Sox2-negative." (PMID 37833934, 2023). "Bioinformatic analysis in human glioma tumors revealed that higher CTH expression is positively correlated to SOX2 expression and associated with worse overall survival in all grades of gliomas." (PMID 37300955, 2023). "It was found that HOXATs and CD133, SOX2 were differentially association within glioma tissues of different grades." (PMID 34805277, 2021). "This interaction led to a positive feedback loop governed by SOX2 and 9 on glioma cells, which decreased Notch1 promoter methylation, leading to its transcription to reinforce glioma–neuron association." (PMID 33805316, 2021). "SOX1 has been implicated with glioma, while SOX2 has been depicted as unfavorable prognostic marker." (PMID 33639927, 2021). "Sox2 has been implicated to promote invasion, migration, and metastasis in colorectal cancer, glioma, melanoma, gastric cancer, hepatocellular cancer, and ovarian cancer." (PMID 34287231, 2021). "TCGA squamous cancers and gliomas with SOX2 focal amplifications are associated with higher SOX2 expression, as compared to samples with non-focal amplifications or samples without amplifications." (PMID 34880227, 2021). "While both cluster one and cluster three were enriched for transcription factors associated with glioma-propagating cells (e.g., SOX2), markers of oligodendrocyte-progenitor cells (OPCs) were more enriched in cluster three." (PMID 34763709, 2021). "In the primary SOX2 high expression gliomas, 2 cases had IDH1 mutation, their PFS and OS were both longer than the medium level (PFS: 20 & 13.5 months; OS: 49.5 & 57.0 months)." (PMID 31718604, 2019). "SOX2 is important for the survival of glioma stem cells and closely associated with the relapse of glioma after chemotherapy or radio-therapy in adults." (PMID 30053878, 2018). "WNT signaling pathway, self-renewal, and retinoic acid associated genes are within the genes involved in SOX2-mediated glioma cell plasticity and astrocytic differentiation." (PMID 27822457, 2016). "Before, Schmitz and coworkers identified SOX2 as a glioma-associated antigen abundantly and specifically overexpressed in glioma cells." (PMID 27822457, 2016). "Sox2 has been implicated in the oncogenesis of glial neoplasms in the brain, and has also been detected in cells of epithelial and mesenchymal tumors, but is also a marker of neural stem cells where its function appears to be maintenance of pluripotency." (PMID 25713758, 2015). "Sox2 has been more consistently associated with multipotentiality and progenitor cell proliferation, and it is essential for glioma-initiating cells to retain their stemness." (PMID 25121761, 2014).
glioma (continued). "This is in accordance with a study performed in a gastric cancer cell line, and other studies using different tumor models, namely gliomas, colorectal cancer and melanomas, where SOX2 was associated with disease progression and poor clinical outcome." (PMID 25300947, 2014). "Since various stem cell markers have been associated with a tumorigenic phenotype in human gliomas, we analyzed invasive and angiogenic xenografts for the expression of the stem cell markers nestin, sox2 and CD133." (PMID 23429996, 2013). "In this regard, our studies on hGBM tissue grade IV specimens showed significant expression of Twist1 and Sox2, known mesenchymal and stemness related markers, respectively, indicating their association with glial tumor genesis and metastasis." (PMID 22184289, 2011). "Enhanced levels of transcripts encoding Sox2, Musashi 1, Nestin and Vimentin were observed in the glioma cultures assayed and in neural stem cells as compared to adult cortical tissues." (PMID 21297991, 2011). "For instance, loss of Sox2 function limits the self-renewing capacity of human glioma cells and reduces their tumor-inducing potential when transplanted into the rodent brain." (PMID 21483788, 2011). "Remarkably, U343-MG and U373-MG glioma cells with knockdown of SOX2 were able to compensate the loss of invasive proteolysis-dependent migration capacity by acquiring an amoeboid-like migration modus." (PMID 22070920, 2011). "In summary, we characterised the transcription factor SOX2 as a glioma-associated antigen that is abundantly and specifically overexpressed in these brain tumours." (PMID 17375044, 2007). "Moreover, the presence of Sox2 in gliomas is strongly associated with disease recurrence and resistance to temozolomide treatment." (PMID 40559213, 2025). "This suggests that PP1γ expression may influence the expression of YAP1 and SOX2, and is associated with the growth and malignant progression of glioma." (PMID 40626009, 2025). "A decreased SOX2/SOX21 ratio results in the loss of stem cell features in glioma cells." (PMID 38132438, 2023). "Serum-induced differentiation of GSCs is associated with loss of tumorigenicity and differentiated glioma cells (DGCs) expressed low levels of the GSC marker SOX2 and BMI1 as well as high levels of astrocytes marker GFAP, which is consistent with previous studies." (PMID 37980347, 2023). "Moreover, increased expression levels of miR-21 further induced the migration of glioma cells, which are associated with the upregulation of Sox-2 and β-catenin protein." (PMID 32182839, 2020). "SOX2 is a well-established master gene involved in the maintenance of tumor stem cell such as phenotype, and its silencing has been associated to a reduction of glioma tumorigenicity." (PMID 33081024, 2020). "SOX2 is also a potential carcinogenic factor associated with malignancy, lymph node metastasis, and pathological grading and clinical staging, especially in glioma cells, it has a crucial role in maintaining stem cell characteristics." (PMID 32439916, 2020). "Clinical analysis could be conducted to evaluate the association between the expression of NEAT1 or SOX2 and the prognosis outcome of glioma patients." (PMID 30053878, 2018). "Interestingly, we found that SOX2, a gene with a well-known and crucial role in stem cell biology that is commonly associated with glioma stem cells, is the most frequently detected gene with at least eightfold specificity for the transformed cells." (PMID 30041684, 2018). "Up-regulation of SOX2 has been linked to the development and maintenance of gliomas." (PMID 29137410, 2017). "Furthermore, inhibition of uPAR and cathepsin B in glioma stem cells was associated with decreased expression of SOX2 and Bmi1, suggesting that cathepsin B and uPAR have pivotal roles in maintaining the malignant nature of CSCs in gliomas." (PMID 28611989, 2017).
glioma (continued). "In the present study, the effects of melatonin on the transcriptional regulation of three genes associated with cell proliferation (Nestin, Bmi-1 and Sox2), and on C6 glioma cell survival and viability, were investigated in vitro to evaluate the use of melatonin in cancer therapy." (PMID 24137328, 2013). "Our present data indicate that both Sox2 and Twist1 expression escorts glial tumorigenesis and that their higher expression levels may be associated with grade IV glial tumors." (PMID 22184289, 2011). "Although not proven so far, it also appears conceivable that the observed loss of intercellular adherence and loss of focal adhesion after RNAi of SOX2 in U343-MG and U373-MG glioma cells directly affects TCF/LEF-signaling through elevated levels of cytosolic β-Catenin." (PMID 22070920, 2011). "SOX2, a transcription factor broadly expressed across stem-like and more differentiated glioma cells, was used to define tumor cell segments." (PMID 40960500, 2025). "Functional assays demonstrated that SOX2 silencing inhibited proliferation of glioma cells, whereas increased SOX2 expression enhanced proliferation of glioma cells by colony formation assay, CCK-8 assay, and EdU assay." (PMID 41458623, 2025). "HOXDeRNA promoted astrocyte transformation by releasing PRC2 repression at glioma transcription factor promoters (SOX2, OLIG2) and activating super enhancers, leading to oncogene upregulation." (PMID 41154382, 2025). "We knocked down SOX2 expression using siRNA and overexpressed it via plasmid in glioma cells in order to ascertain the role of SOX2 in glioma." (PMID 41458623, 2025). "SOX2+ CD45- cells (identified as glioma-stem cells) accounted for 22.6% ± 8.0% of all live cells and were largely PD-L1 positive cells (PD-1+ vs PD-L1+ vs PD-1+ PD-L1+; 3.1% ± 1.2% vs 45.6% ± 4.8% vs 19.0% ± 2.7%)." (PMID 39470381, 2025). "The Sox2 gene, as a stemness marker, was highly expressed in the rat glioma 101.8 tissue strain as well, consistent with such findings in human glioblastoma." (PMID 41009560, 2025). "HIF1α in TNBC and NR2F2 in PCa enhance EBF1 expression, while ZNF521 in GC and Sox2 in glioma act as negative regulators, indicating that EBF1 functions as a central node at the convergence of multiple signaling pathways." (PMID 40508012, 2025). "Conversely, OCT4 can increase the expression of genes such as Nanog and Sox2 to facilitate glioma cell self-renewal and invasion." (PMID 39781344, 2025). "For instance, lncRNA NEAT1 enhances the growth and invasiveness of glioma cells by modulating the miR-132/SOX2 axis." (PMID 41050080, 2025). "Based on analysis of DEGs in SOX2 high and low expression groups, we attempted to clarify the mechanism by which SOX2 regulates glioma development and occurrence." (PMID 41458623, 2025). "The results demonstrated that SOX2 expression decreased and increased in glioma cells following knockdown and overexpression of ZFHX4." (PMID 41458623, 2025). "Previous reports show that PRKDC is preferentially expressed in glioma stem cell-like populations and stabilizes Sox2, a core transcription factor that maintains the glioma stem cell niche in GBM." (PMID 41271669, 2025). "Following the knockdown of ZFHX4 and the overexpression of ZFHX4, there were substantial changes in the expression of SOX2 in glioma cells as determined by RT-PCR and Western Blot analysis." (PMID 41458623, 2025). "This is consistent with findings in glioma models identifying suppression of SOX2 expression with ATRX depletion." (PMID 41380652, 2025). "Our team’s preliminary work has previously reported a linear pathway where ZFHX4-AS1 upregulates its neighboring gene ZFHX4, which in turn promotes the expression of SOX2, thereby accelerating glioma progression." (PMID 41458623, 2025). "This detailed ZFHX4-AS1/ZFHX4/SOX2/JAK-STAT axis represents a promising set of therapeutic targets for glioma treatment." (PMID 41458623, 2025).